CCL5 (C-C motif chemokine ligand 5)
Diseases named in the same sentence as CCL5 in open-access papers (continued):
Sharing a sentence is not in itself a finding about the gene and the disease.
glioma (continued). "We found that the following neutrophil chemokines—MMP9, CCL2, CCL5, CXCR4, CXCR2, CCL23, and IL8 (p = 0.07)—were enriched in TERTmut gliomas (t-test, p < 0.05)." (PMID 33996815, 2021). "By analyzing CCL5/CCR5 mRNA and protein expression in glioma tissues in a larger cohort of 65 patients, we confirmed that both, CCL5 and CCR5 genes are increasingly expressed in advanced glioma." (PMID 32545571, 2020). "Yi and colleagues found that glioma-initiating cells produced CCL2, CCL5, VEGF-A, and neurotensin at higher levels than the glioma cells; these findings suggest that CSCs play an important role in TAM recruitment by secreting macrophage chemoattractants." (PMID 25125485, 2014). "Glioma cells tend to migrate toward GAM‐conditioned media activated by granulocyte–macrophage colony‐stimulating factor (GM‐CSF); this medium is abundant in CCL5." (PMID 40620486, 2025). "For example, PCs in gliomas can promote DNA repair and induce resistance to temozolomide (TMZ) drugs through secreting CCL5 and binding to CCR5 expressed on glioblastoma multiforme (GBM) cells, conversely, silencing the CCL5-CCR5 signal can improve the efficacy of TMZ." (PMID 37666813, 2023). "In addition, glioma conditioned media treatment of microglia resulted in a rapid upregulation of gene expression of several CCR1 ligands including CCL3, CCL5, CCL6 and CCL9." (PMID 36982211, 2023). "Furthermore, downregulated expression of microglial CCL5 and CCR2 in athymic mice showed impaired engraftment of Nf1 optic low grade glioma stem cells." (PMID 36555253, 2022). "In this study, CCL2, CCL5, CXCR4, MMP9, and CXCR2 expression was found to be high in TERTmut glioma from all samples and IDHwt subgroups with high levels of neutrophil infiltration, which indicated that N2 phenotype neutrophils were associated with TERT mutation." (PMID 33996815, 2021). "The correlation between CCL5 and the pericyte markers (Desmin (DES), platelet derived growth factor receptor beta (PDGFRB) or actin alpha 2 (ACTA2)) was confirmed in both the TCGA-GBM and the Chinese Glioma Genome Atlas (CGGA)-GBM datasets." (PMID 34239070, 2021). "Moreover, we found that PDCD4 regulates the expression of IL-5, CCL-5, VEGF, and CXCL10 in glioma cells, which provides a therapeutic opportunity to block these cytokines." (PMID 33304903, 2020). "In addition, CCL5 and GPNMB have both been reported to play a role in glioma invasion, migration, and recurrence." (PMID 30151353, 2018). "Lastly, CCL5 is produced by microglia in the microenvironment of murine Nf1 optic glioma, and is increased in low-grade gliomas (pilocytic astrocytoma) relative to non-neoplastic tissue." (PMID 28380429, 2017). "Importantly, microglial Ccl5 expression requires T lymphocytes, such that glioma formation does not occur in mice lacking functional T cells." (PMID 32358581, 2020). "However, while CCL5 function in glioma has not been fully elucidated, several reports have suggested that it might be an important chemokine in this setting." (PMID 28380429, 2017). "CCL5 and CCR5 gene expression were significantly higher in a cohort of 38 glioblastoma samples, compared to low-grade glioma and non-cancerous tissues." (PMID 32545571, 2020). "Our results are consistent with studies that showed increased CCL5 and CCR5 expression in human glioma tissues and glioblastoma cells, compared to normal counterparts." (PMID 32545571, 2020). "CCL5 autocrine signaling in high-grade glioma promoted growth regulation via the mesenchymal (MES) GBM–GSC subtype, which also expresses higher levels of the stemness marker CD44, a nonconventional or “auxiliary receptor” for CCL5." (PMID 33923334, 2021).
colorectal cancer (64 papers, 2011 to 2025). A primary or metastatic malignant neoplasm that affects the colon or rectum. "CCL5 deficiency inhibits colorectal cancer growth and metastasis by promoting the infiltration of CD8+ T cells into the central region of the tumor." (PMID 40097979, 2025). "Interestingly, CCL5 is associated with a chemokine profile which predicts the presence of ELS in colorectal cancer." (PMID 36717913, 2023). "Conversely, another report in colorectal cancer associated a higher expression of CCL5 with a greater number of Treg and increased CD8+ T cells apoptosis, suggesting a critical role for CCL5 in recruiting Treg and enhancing their ability to suppress CD8+ T cells." (PMID 29371976, 2017). "Inflammation-activated human mesenchymal stem cells (MSCs) promote the EMT process and progression of colorectal cancer (CRC) through the CCL5/β-catenin/Slug pathway." (PMID 39315246, 2024). "CCL5 contributes to immune suppressive environment, and MΦ‐derived CCL5 facilitates the immune escape of colorectal cancer cells via the STAT3‐PD‐L1 pathway." (PMID 37716915, 2024). "DNA mismatch repair-deficient colorectal cancer cells can overexpress CXCL10 and CCL5 via endogenous activation of type I interferon signaling, thus increasing the recruitment of CD8+ T cells into tumors." (PMID 38762546, 2024). "The p65/STAT3-CSN5-PD-L1 pathway is used by colorectal cancer cells to promote immune escape, with the assistance of macrophage-derived chemokine 5 (CCL5)." (PMID 39100676, 2024). "Dendritic cells, specifically tumor-associated dendritic cells (TADCs), that surround colorectal cancer express recombinant human chemokine ligand 5 (CCL5), which promotes the migration and invasion of colorectal cancer cells." (PMID 39100676, 2024). "In colorectal cancer, macrophages-derived C-C motif chemokine ligand 5 (CCL5) promotes the activation of NF-κB p65 activation, which binds to the CSN5 promoter, increases CSN5 expression, and upregulates PD-L1 protein level." (PMID 37415977, 2023). "The chemokine CCL5 plays a potential role in the occurrence and development of colorectal cancer (CRC)." (PMID 37141250, 2023). "In particular, CCL5 contributes to immune escape in colorectal cancer by boosting the toxicity of regulatory T cells against cytotoxic T cells, leading to the cell apoptosis of cytotoxic T cells in tumors." (PMID 37627528, 2023). "In conclusion, knockdown of circABCB10 promotes ferroptosis in colorectal carcinoma cells through miR-326/CCL5 axis and inhibits the further development of colorectal cancer, providing a new perspective on the progression of colorectal cancer." (PMID 37152286, 2023). "Ccl5-deficiency mice had increased CD8+ T cells in tumors and reversal of aPD1 resistance in a colorectal cancer model." (PMID 36132332, 2022). "It has been reported that CCL5 is overexpressed in colorectal cancer and plays a crucial role in immune escape of tumor cells." (PMID 35208526, 2022). "Platelets together with leukocytes and tumor cells, induced another chemokine—CCL5/RANTES from EC in an experimental model of colorectal cancer, which enhanced metastatic seeding due to recruitment of monocytes." (PMID 33146401, 2021). "In colorectal cancer, tumor-infiltrated macrophages secreted CCL5, which activates p65/STAT3 pathway and indirectly stabilizes PD-L1 protein rather than increasing the mRNA expression of PD-L1 in cancer cells." (PMID 34771505, 2021). "Secretion of CXCL10 and CCL5 in the tumor has been associated with accumulation of granzyme producing CD8+ and IFN-γ producing CD4+ T cells in colorectal carcinomas, and early TNM staging." (PMID 32033490, 2020). "PDGF-BB, EphA7, CCR5, and CCL5 levels of the patients with colorectal carcinoma were significantly higher compared to the control group (p < 0.001 for each comparison)." (PMID 31505877, 2019).
colorectal cancer (continued). "Consistent with our observations, CCL5 and CXCL10 are reported to recruit antitumor CD8+ T lymphocytes into malignancies and are positively associated with the survival of patients with colorectal cancer or hepatocellular carcinoma." (PMID 26317795, 2015). "CCL5 was also shown to be important in tumor progression of several cancers, such as breast and colorectal carcinoma." (PMID 24204919, 2013). "Recently, beta chemokine CCL5 neutralization has been found to restrict cancer cell growth in colorectal cancer." (PMID 23226201, 2012). "To do so, we have examined a number of human colorectal carcinoma clinical specimens and found CCL5 and its receptors over-expressed within primary as well as liver and pulmonary metastases of patients compared to healthy tissues." (PMID 22205974, 2011). "Collectively, our data demonstrate the involvement of CCL5 in the pathogenesis of colorectal carcinoma and point to its potential value as a therapeutic target." (PMID 22205974, 2011). "In the present work, we provide the first evidence of the implication of CCL5 in the pathophysiology of colorectal carcinoma." (PMID 22205974, 2011). "The study described herein aimed precisely at getting new insights into the role played by CCL5/CCR5 interactions in the development of colorectal carcinoma." (PMID 22205974, 2011). "Notably, genes such as DKK1, GZMB, THBS1, and CCL5—recognized for their key contributions to colorectal cancer prognosis—have been incorporated into several existing prognostic models." (PMID 40670378, 2025). "Interestingly, the data support the involvement of CCL5/RANTES in the pathogenesis of colorectal cancer (CRC) and indicate its potential value as a therapeutic target." (PMID 40426971, 2025). "CCL5 recruits fibroblasts in colorectal cancer through CCR5-SLC25A24 signaling, which increases VEGFA and transdifferentiates fibroblasts into vascular endothelial cells, promoting tumor angiogenesis and collagen synthesis, ultimately promoting tumor development." (PMID 39835121, 2024). "The coordinated expression of CCL5 with TNF-α in our research may point to an inflammatory network between chemokines and cytokines in colorectal cancer and can be associated with the promotion of CCL5 secretion by TNF-α." (PMID 35208526, 2022). "However, a recent study demonstrated that T cells at invasive margins of colorectal cancer tumors at liver-metastatic sites secrete chemokine CCL5." (PMID 35385679, 2022). "Evidence indicates that CCL5/RANTES helps in immune escape of colorectal cancers." (PMID 26951793, 2016). "Interestingly, CCL5 has recently been reported to be expressed in colorectal carcinoma, predominantly at the invasive front of primary tumors." (PMID 22205974, 2011). "CCL5 knockdown could help in anti-colorectal cancer treatments." (PMID 40097979, 2025). "Transcriptional profiling of human colorectal cancer (CRC) tissues revealed that active secretion of CCL5 and CXCL10 from the tumor microenvironment is closely associated with GZMB + CD8+ T cell infiltration, suggesting a critical role of CCL5 and CXCL10 in CTL recruitment." (PMID 35292660, 2022). "Studies have shown that in colorectal cancer, IGF2BP3 modulates the expression of T cell chemokines such as CCL5 and CXCL9/10, thereby influencing T cell recruitment to the tumor site." (PMID 41589308, 2025). "In colorectal cancer, a high cholesterol diet (HCD) favors the infiltration of macrophages, which secrete the chemokine C-C motif ligand 5 (CCL5)." (PMID 40270603, 2025). "Chemokines, including CXCL10, CXCL12, CX3CL1, CCL2, CCL5, CCL18, and CCL20, induce chemotaxis to promote cell migration and invasion in ovarian, lung, breast, and colorectal cancers." (PMID 38438872, 2024). "For colorectal cancer patients treated with OH2 combined with PD-1 antibody, the CCL5 level of PR patients showed a more significant upward trend than SD/PD patients, indicating that CCL5 is a potential candidate for the companion diagnostics for OH2 therapy." (PMID 36438484, 2022).
colorectal cancer (continued). "Here, in this study we compared the levels of CCR5, CCL5, PDGF, and EphA7 in patients with colorectal carcinoma and healthy controls in order to assess these parameters in terms of early diagnosis." (PMID 31505877, 2019). "The conclusion is that CCL5/CCR5 signaling recruits T-regs which in turn eliminate CD8+ T cells, thereby defining a novel mechanism of immune escape in colorectal cancer and pointing to the potential value of CCL5 as a therapeutic target." (PMID 24523569, 2014). "Moreover, CCL5 has been reported to be involved in cancer metastasis and progression through the STAT3 signaling pathway in breast, bladder, and colorectal cancers." (PMID 39126553, 2024). "For human MDSC-DCs, peripheral bloods from colorectal cancer patients were induced in vitro as murine cells with or without T- lymphocytes depletion to get rid of CCL5." (PMID 35707772, 2022). "Moreover, a recent study has revealed that CCL5 and CXCL10 expressed by colorectal cancer tissues promote the migration of GrzB+ CD8+ T cells." (PMID 30984181, 2019). "This is the first study that has investigated whether the cytokines/chemokines CCL5, CCR5, PDGF, and EphA7 have significant value for early diagnosis of colorectal carcinomas." (PMID 31505877, 2019). "Finally, it should be remarked that RANTES/CCL5 is also known to be induced by chitinases, while CHI3L1 can induce macrophage recruitment by MCP-1 chemotaxis in colorectal cancer and has a role in IL-17A-dependent mechanisms." (PMID 29892291, 2018). "In a murine model of colorectal cancer, OV expression of the chemokine RANTES (CCL5) prolonged the persistence of an oncolytic vaccinia virus, increased intratumoral lymphocyte infiltration, and enhanced antigen-specific antitumor responses, particularly in combination with DC-based immunotherapy." (PMID 28589085, 2017). "CCL5/CCR5 axis has also been proposed to affect the motility of human osteosarcoma and oral cancer cells in vitro and CCL5 neutralization was shown to restrict tumor progression in colorectal carcinoma." (PMID 24204919, 2013). "Collectively, our observations argue for a significant implication of CCL5 in the growth and spread of CRC cells in vivo and in vitro, whereas CCR5 signaling appears to be involved to a much lesser extent in the pathogenesis of colorectal cancer." (PMID 22205974, 2011).
Sepsis (62 papers, 2009 to 2025). Sepsis is defined as life-threatening organ dysfunction caused by a dysregulated host response to infection. "One animal study showed that administering CCL5 to mice caused an increase in mortality in wild-type mice with sepsis, whereas neutralizing CCL5 resulted in improved survival." (PMID 38313013, 2024). "By contrast, previous studies have demonstrated that the MSCs significantly reduced systemic cytokines and chemokines (IL-6, IL-1b, IL-10, KC, and CCL5) after 28 h of administration in the sepsis-associated inflammation mouse model." (PMID 32903481, 2020). "Several other products implicated in the pathogenesis of sepsis were also induced by this treatment, including IL-12p40, CCL5/RANTES, CXCL1/KC, CCL9/MIP-1γ, CXCL2/MIP-2, P-Selectin, TIMP-1 and CCL2/MCP-1." (PMID 19284588, 2009). "Despite elevated CCL5 levels having been reported in sarcopenic skeletal muscle induced by sepsis and cholestatic chronic liver disease, its role in the generation and development of sarcopenia has been unexplored." (PMID 39857418, 2025). "Specific pro-inflammatory cytokines, including IL-1β, CCL4, CCL5, and CXCL10, have emerged as potential diagnostic markers for sepsis and critical indicators of cytokine storm severity." (PMID 38496165, 2024). "Another study found that sepsis activates Rac1 in platelets, resulting in the secretion of CCL5 by the platelets." (PMID 38313013, 2024). "Simultaneously, enhanced interaction between KC_Cxcl10 and Neu subtypes through chemokine ligands and receptors such as Ccl5–Ccr1 indicated increased chemotaxis from KC_Cxcl10 to Neu during sepsis." (PMID 37808269, 2023). "During the course of LPS sepsis (0–36 hpi), most PICCs reached the first and second peak at 6 and 16 hpi, respectively, with IL-6, IL-18, CCL5, CCL7 and CXCL1 sustaining at plateau at 36 hpi." (PMID 37332010, 2023). "CCL5, a member of CC motif chemokines ligand, is recognized as an effective biomarker for the diagnosis of sepsis." (PMID 36650470, 2023). "In the end, we managed to formulate a signature of 7 IRGs for the prognosis of sepsis patients: − 0.465 × CCL5 + 0.215 × DEFA4 − 1.487 × NFYC + 1.055 × ESR1 − 0.737 × TNFRSF8 − 0.228 × CX3CR1 + 1.003 × SERPINA3." (PMID 36650470, 2023). "Other studies have identified the use of IL-1β, CCL4, CCL5 and CXCL10 as possible diagnostic markers for sepsis." (PMID 35811678, 2022). "For distinguishing between sepsis from febrile controls, both CCL5 (0.82, p<0.01) and CXCL10 (0.82, p<0.001) showed the greatest potential in differentiating the two groups." (PMID 35811678, 2022). "Following sepsis, we tested candidate MK growth factors and observed decreased splenic expression of Tpo, Csf2, and Ccl5, while Il1b was unchanged and Il3 and Il6 were significantly increased." (PMID 35192546, 2022). "The chemokines had higher AUC values in differentiating between children with malaria and sepsis (p<0.0001), with CCL5 showing the greatest potential with an AUC value of 0.96." (PMID 35811678, 2022). "Clinical studies are conflicting and demonstrate either decreased or increased CCL5 levels in the blood during neonatal sepsis." (PMID 32373108, 2020). "For the chemokines, CCL2 and CCL3 levels were elevated in the middle sepsis phase (12 h), while CCL5, CXCL9, and CXCL10 levels were significantly increased in the late phase." (PMID 31354717, 2019). "Platelet activation during sepsis triggers the release of RANTES (CCL5) and platelet factor 4 (PF4, CXCL4) and subsequent heteromer formation in the circulation." (PMID 31379873, 2019). "However, sepsis animal studies found that administration of CCL5 increased sepsis-induced lethality in wild type mice, whereas neutralization of CCL5 improved survival, consistent with the results of the present study." (PMID 38313013, 2024). "Among these 7 IRGs, which could predict the prognosis of sepsis patients, CCL5, DEFA4, ESR1 and CX3CR1 were broadly researched in previous studies." (PMID 36650470, 2023).